EIF4E (eukaryotic translation initiation factor 4E)
Diseases named in the same sentence as EIF4E in open-access papers (continued):
Sharing a sentence is not in itself a finding about the gene and the disease.
acute myeloid leukemia (23 papers, 2009 to 2026). Acute myeloid leukemia (AML) is a group of neoplasms arising from precursor cells committed to the myeloid cell-line differentiation. "In acute myeloid leukemia (AML), the increased expression and phosphorylation of eIF4E are associated with poor prognosis, and phosphorylated eIF4E can be used as a prognostic indicator and potential anti-cancer target for biological therapy of AML." (PMID 37601696, 2023). "Targeting eIF4E and other components of the translation machinery has shown potential in clinical trials in acute myeloid leukemia patients." (PMID 41279557, 2025). "Eukaryotic translation initiation factor 4E (eIF4E), a prooncogenic protein increased in acute myeloid leukemia (AML), specifically binds to m7 G caps and stimulates the export and translation of RNMT and RNGTT." (PMID 40483535, 2025). "Ribavirin was reported to work as a cap mimetic and has led to inhibition of eIF4E-mediated progression of acute myeloid leukemia, and recently has been touted as effective drug in treatment of Covid-19 in preliminary clinical trials." (PMID 36998012, 2023). "The eukaryotic translation initiation factor eIF4E is increased in 30% of cancers, including the M4/M5 subtypes of acute myeloid leukemia." (PMID 35982949, 2022). "The M4/M5 subtype of acute myeloid leukemia overexpresses eukaryotic translation initiation factor eIF4E." (PMID 32069925, 2020). "eIF4E is substantially elevated and enriched in the nucleus of some cancer cells, including subtypes of acute myeloid leukemia (AML) and lymphomas." (PMID 28325843, 2017). "In early-stage clinical trials, eIF4E targeting with ribavirin led to objective responses including remissions in some acute myeloid leukemia (AML) patients." (PMID 29111978, 2017). "In line with this, ribavirin blocked eIF4E-mediated oncogenic transformation in vitro and demonstrated in vivo efficacy in preclinical models of acute myelogenous leukaemia (AML) and squamous cell carcinoma." (PMID 21772331, 2011). "To date, eIF4E has been successfully targeted only in a particularly aggressive form of acute myeloid leukemia French American British (FAB) subtype M4/M5 AML." (PMID 20049173, 2009). "MAPK interacting kinase (MNK), a downstream effector of mitogen-activated protein kinase (MAPK) pathways, activates eukaryotic translation initiation factor 4E (eIF4E) and plays a key role in the mRNA translation of mitogenic and antiapoptotic genes in acute myeloid leukemia (AML) cells." (PMID 31903169, 2019). "Here we identify a small molecule, homoharringtonine (HHT), that antagonizes p-eIF4E function and eradicates acute myeloid leukemia (AML) expressing high level of p-eIF4E in vitro and in vivo." (PMID 25915158, 2015). "In acute myeloid leukemia (AML), elevated eIF4E levels are characteristic of the poor prognosis M4 and M5 AML subtypes." (PMID 20049173, 2009). "IGF2BP2 recruits proteins such as eIF4E and eIF3A to MYC, GPT2, and SLC1A5 mRNA, regulating glutamine metabolism in acute myeloid leukemia and modulating the immune response of macrophages through epigenetic reprogramming." (PMID 39726589, 2024). "This occurs in multiple human cell lines and in high-eIF4E acute myeloid leukemia (AML) patient specimens, suggesting that in parallel to CBC escorted RNAs, eIF4E can also chaperone a subset of RNAs to the spliceosome." (PMID 34944805, 2021). "In acute myeloid leukemia cells, MNK2 inhibited by cercosporamide could decrease phosphorylation of eIF4E on serine 209, and such an inhibitory effect correlated with suppression of leukemic cell proliferation in vitro." (PMID 28878291, 2017). "To identify the putative cancer-associated nuclear body, we initially stained two human leukemia cell lines KG-1 (acute myeloid leukemia, AML) and MEG-01 (chronic myeloid leukemia, CML) by immunofluorescence staining with antibodies against phosphorylated eIF4E (p-eIF4E) or total eIF4E (t-eIF4E)." (PMID 26678034, 2016).
gastric cancer (22 papers, 2014 to 2025). A primary or metastatic malignant neoplasm involving the stomach. "It is also overexpressed in different tumor types, like colon, prostate, breast, lung, or gastric cancer, and eIF4E is often associated to poor prognosis and malignancy." (PMID 31027221, 2019). "We previously demonstrated that AEG-1 promoted the growth and metastasis of gastric cancer by upregulating the expression of oncogenic eukaryotic translation initiation factor 4E." (PMID 40914249, 2025). "In summary, the present study demonstrates that AEG‐1 promotes EMT and metastasis of gastric cancer through upregulation of eIF4E‐mediated expression of MMP‐9 and Twist." (PMID 28661037, 2017). "We have reported that elevated eIF4E protein expression in human gastric cancer tissue is correlated with cancer metastasis." (PMID 28661037, 2017). "For miR-497, it was reported to inhibit ovarian cancer cell migration and invasion through targeting of SMAD specific E3 ubiquitin protein ligase and modulate gastric cancer cell invasion by repressing eIF4E." (PMID 26336827, 2015). "Thus, the mTOR/eIF4E pathway exposed the vulnerability of gastric cancer by accelerating the production of aberrant peptides and boosting immune activation through W>F substitutant events." (PMID 38994917, 2024). "While, a recent study revealed that lncRNA FOXD1-AS1 could strengthen the interaction of eIF4E with eIF4G by activating the PI3K/AkT/mTOR pathway to promote gastric cancer progression and cisplatin resistance." (PMID 34454479, 2021). "Researches showed that miR‐503 regulated EIF4E to prevent the proliferation of hepatocellular carcinoma cells, and the low expression of miR‐503 was closely related to the poor prognosis of patients with gastric cancer." (PMID 33135394, 2020). "Furthermore, upstream regulators including PDGF-B, PDGFR-β, Akt, eIF4E and p70s6K were found significantly increased in the gastric cancer tissues." (PMID 28423550, 2017). "Intriguingly, although mTOR/eIF4E pathway was a pivotal driver for EBV‐positive gastric cancer, it also promoted the production of a substantial subset of abnormal W>F peptides, which exposed the fatal drawback of gastric cancer, increasing their susceptibility to the immune system." (PMID 38994917, 2024). "The expression of EIF4E, EXOSC1, IARS1, IGFBP1, and SPCS1 was found to be upregulated in stomach cancer cell lines, while TSPYL2 and TUBB2A showed downregulated expression." (PMID 38700505, 2024). "AURKA is activated in gastric cancer and it has been demonstrated that AURKA promotes cisplatin resistance in gastric cancer by regulating eIF4E, c-MYC, HDM2." (PMID 32508530, 2020). "Western blot analysis demonstrated overexpression of AURKA and phosphorylation of eIF4E in acquired and de novo CDDP‐resistant gastric cancer models." (PMID 28417568, 2017). "We first screened a panel of gastric cancer cell lines for their sensitivity to CDDP and correlation with protein expression of AURKA, p‐eIF4E, eIF4E, c‐MYC, and HDM2." (PMID 28417568, 2017). "Taken together, these results indicate that AURKA‐mediated acquired CDDP resistance is dependent on eIF4E and its downstream targets in AGS gastric cancer cells and suggest that targeting AURKA can be an effective therapeutic approach in CDDP‐resistant cells." (PMID 28417568, 2017). "This study's findings suggest that in gastric cancer, AEG‐1 promotes EMT via eIF4E‐regulated MMP‐9 and Twist." (PMID 28661037, 2017). "Using the AEG‐1 stable knockdown cell lines in this model, we revealed that silencing of AEG‐1 expression not only inhibited tumour growth in parallel with decreased expression of eIF4E, MMP‐9 and Twist, but it also inhibited the lymph node and peritoneal metastasis of gastric cancer." (PMID 28661037, 2017). "Combining our present and previous work, we hypothesis that the GMBP1 peptide modulates gastric cancer MDR by targeting GRP78 and that the expression of GRP78 modulates the expression of EIF4E and MDR1 through the PI3K/AKT pathway." (PMID 25943993, 2015).
gastric cancer (continued). "Given the role of EIF4E in gastric cancer has not been fully elucidated, we first sought to explore whether EIF4E had tumor‐promoting effects in GC." (PMID 38994917, 2024). "Finally, silencing of AEG‐1 expression not only inhibited tumour growth in parallel with downregulation of eIF4E, MMP‐9 and Twist expression in a xenograft nude mouse model, but also suppressed lymph node and peritoneal metastasis of gastric cancer in an orthotopic nude mouse model." (PMID 28661037, 2017). "Tapia and colleagues investigated the activation of PI3K/AKT/mTOR signals in gastric cancer (GC), with the overexpression of most important target proteins of the pathway, such as PI3K, AKT, p-AKT, p-mTOR, p-4E-BP1, P70S6K1, p-P70S6K1, eIF-4E, and p-eIF-4E proteins in tumor tissue." (PMID 33066449, 2020). "Although Snail was reported to be a downstream target of AEG‐1 or eIF4E in other types of cancers, it was not the key molecule involved in the AEG‐1/eIF4E pathway in gastric cancer metastasis in this study, as it did not changed in the same pattern as MMP‐9 and Twist did." (PMID 28661037, 2017).
leukemia (22 papers, 2009 to 2025). A malignant (clonal) hematologic disorder, involving hematopoietic stem cells and characterized by the presence of primitive or atypical myeloid or lymphoid cells in the bone marrow and the blood. "Although the function of HuR has not been directly assessed in MLL-r leukemia, it has been shown to regulate and associate with other ARE RBPs that have been shown to be aberrantly expressed in MLL-r leukemia such as EIF4E, NCL, and ZFP36L1." (PMID 36307883, 2022). "Given its involvement in leukemia progression and dispensable role in normal hematopoiesis, eIF4E is an attractive therapeutic target in AML." (PMID 31903169, 2019). "It was recently reported that HHT targets the phosphorylated serine 209 residue of eIF4E, resulting in the degradation of phosphorylated eIF4E, thereby eradicating the growth of leukemia cells in vitro and in vivo." (PMID 30388805, 2018). "eIF4E overexpression and phosphorylation reportedly regulates β-catenin in leukemia stem cells to maintain stem cell functions." (PMID 27926520, 2017). "To reveal the morphology and structure features of GNB, we isolated and purified GNBs from leukemia cells using dounce homogenization followed by immunopurification with p-eIF4E antibody." (PMID 26678034, 2016). "To further confirm these observations, we performed a time course analysis of HHT-induced UBC9 conjugation to p-eIF4E in leukemia cells." (PMID 25915158, 2015). "To confirm above observations, we next used biotin-labeled HHT (HHT-biotin) to capture p-eIF4E protein in leukemia cells." (PMID 25915158, 2015). "We observed that HHT-mediated anti-leukemia activity was positively correlated with p-eIF4E inhibition (R2 = 0.87)." (PMID 25915158, 2015). "Treatment of THP-1 leukemia (AML-M5) cells with HHT for 24h led to a dose-dependent inhibition of p-eIF4E." (PMID 25915158, 2015). "The kinase inhibitor BAY 43-9006 was shown to induce apoptosis in human leukaemia cells involving downregulation of Mcl-1 through the rapid and potent dephosphorylation of the eIF4E translation-initiation factor." (PMID 21750559, 2011). "Further, eIF4E mRNA levels are substantially reduced in primary leukemia specimens transduced with the IκB-SR." (PMID 20049173, 2009). "In studies in primary human leukemia specimens, subtypes of leukemias with elevated levels of eIF4E are sensitive to inhibition of eIF4E by antagonists at levels 100-fold less than those that effect normal bone marrow or other leukemic subtypes." (PMID 20049173, 2009). "The first clinical trial targeting eIF4E indicates that ribavirin effectively targets eIF4E in poor prognosis leukemia patients and more importantly leads to striking clinical responses including complete and partial remissions." (PMID 20049173, 2009). "Inhibition of Mnk/eIF4E pathway in blast crisis chronic myeloid leukemia could effectively prevent self-renewal of leukemia stem cells." (PMID 27050281, 2016). "These include activation of the tumor suppressor, protein phosphatase 2A or inhibition of leukemia stem cell self-renewal by targeting the Wnt/β-catenin pathway through inhibition of MAP kinase interacting serine/threonine kinase (MNK)-eukaryotic translation initiation factor 4E (eIF4E) axis." (PMID 26378050, 2015). "Furthermore, we found that the proteasome inhibitor MG132 strongly blocked the HHT-induced decrease in p-eIF4E levels in leukemia cells, suggesting that HHT treatment triggers the proteasome-dependent degradation of p-eIF4E protein." (PMID 25915158, 2015). "Importantly, compound structure-activity relationship (SAR) analysis results showed that HHT-mediated anti-leukemia activity is positively correlated with p-eIF4E levels." (PMID 25915158, 2015). "As there is evidence that Mnk activity is required for rapamycin-induced eIF4E phosphorylation in leukemia cells, we determined whether Mnks are required." (PMID 25193863, 2014). "These poor-prognosis leukemias are characterized by elevated eIF4E levels." (PMID 20049173, 2009).
leukemia (continued). "The elevation of eIF4E level will lead to the imbalance of eIF4E-dependent mRNAs transport, which will hinder the differentiation of granulocytes and monocytes, especially in myeloid leukemia and may contribute to the occurrence of leukemia." (PMID 37601696, 2023). "Homoharringtonine exerts antitumor effects by inhibiting the synthesis of target proteins, such as phospho-eIF4E, SP1/TET1/5hmC, Smad3, and TGF-β pathway components, and NF-κB repressing factor, and promotes apoptosis in leukemia cells." (PMID 35873796, 2022). "In particular, recent studies have shown that inhibiting p-eIF4E with small molecule inhibitors of MNK that phosphorylates eIF4E, exhibited a potent inhibition for leukemia." (PMID 25915158, 2015). "We show that FK866 induces a translational arrest in leukemia cells through inhibition of MTOR/4EBP1 signaling and of the initiation factors EIF4E and EIF2A." (PMID 26542945, 2015). "After 24 h of HHT exposure, most p-eIF4E was present in the detergent-insoluble pellet, suggesting that HHT increased the levels of denatured p-eIF4E in leukemia cells." (PMID 25915158, 2015). "Moreover, NMD has yet to be explored for those non-polarized cells having high levels of nuclear eIF4E, e.g., high-eIF4E primary leukemia samples or U2OS cells overexpressing FLAG-tagged eIF4E, in which specific nuclear mRNAs acquire eIF4E at their 5′ cap." (PMID 38263082, 2024). "To determine whether HHT-mediated decrease of p-eIF4E is involved in SUMOylation modification, we evaluated the effects of HHT on both p-eIF4E and the small ubiquitin-like protein modifier (SUMO)-conjugating enzyme UBC9 in leukemia cells." (PMID 25915158, 2015). "Given that MNK-mediated eIF4E phosphorylation strongly contributes to tumorigenesis, lymphomagenesis, and tumor metastasis while being dispensable for development, pharmacological MNK1/2 inhibition may represent an attractive strategy for the treatment of leukemias." (PMID 31903169, 2019).
hepatocellular carcinoma (21 papers, 2015 to 2025). A malignant tumor that arises from hepatocytes. "For example, programmed cell death 1 (PD‐1) can bind to EIF4E and promote its phosphorylation in hepatocellular carcinoma cells." (PMID 33539648, 2021). "Collectively, our findings indicate that OGT promotes the stem‐like cell potential of hepatoma cell through O‐GlcNAcylation of eIF4E." (PMID 30677218, 2019). "Our data indicate that eIF4E regulates the stem‐like cell potential of hepatoma cell, providing a new mechanism that eIF4E promotes cancer development." (PMID 30677218, 2019). "Together, OGT promotes hepatoma cell proliferation and stem‐like cell potential at least partly through stabilization of eIF4E expression." (PMID 30677218, 2019). "CCK8 assay showed that the inhibitory effect of OGT knockdown on the proliferation of hepatoma cell was rescued by expression of exogenous eIF4E." (PMID 30677218, 2019). "Expression of eIF4E in hepatoma was determined by immunostaining in 232 HCC patients, and Kaplan‐Meier survival analysis was used to determine the correlation of eIF4E expression with prognosis." (PMID 30677218, 2019). "OGT activated stem‐like cell potential in hepatoma cell partly through up‐regulation of eIF4E expression." (PMID 30677218, 2019). "Our findings indicate that OGT promotes the stem‐like cell potential of hepatoma cell through O‐GlcNAcylation of eIF4E, providing a mechanism of HCC development." (PMID 30677218, 2019). "OGT activated stem‐like cell potential in hepatoma through eukaryotic initiation factor 4E (eIF4E) which bound to stem‐related gene Sox2 5'‐untranslated region." (PMID 30677218, 2019). "Next, we determined the importance of eIF4E in glucose regulating stem‐like cell potential of hepatoma cell." (PMID 30677218, 2019). "High eIF4E versus 4E-BP expression is suggested as a cancer prognosis measure, and we have shown that tumour samples of patients with hepatocellular carcinoma exhibit variable eIF4E/4E-BP1 ratios." (PMID 30138450, 2018). "It inhibits the oncogene Eif4e, whose overexpression leads to human hepatocellular carcinoma development together with Ras activation." (PMID 28212608, 2017). "To further determine whether eIF4E was O‐GlcNAcylated in the liver cancer samples, we used sWGA for affinity purification of hepatocellular carcinoma and adjacent normal tissues lysates." (PMID 30677218, 2019). "Furthermore, in hepatocellular carcinoma cells or aggressive B-cell lymphomas, high eIF4E/4E-BP1 confers resistance to metformin-induced apoptosis or mTOR inhibitors, respectively." (PMID 30138450, 2018). "PD-1 binds to both RPS6 and eIF-4E to promote their phosphorylation in a hepatocellular carcinoma (HCC) cell line." (PMID 35008473, 2021). "Next, we examined whether O‐GlcNAcylation of eIF4E also occurs in hepatoma cell." (PMID 30677218, 2019). "Excessive activation of RAS/MAPK signaling is commonly observed in hepatocellular carcinoma (HCC), and it has been found that RIT1 induces angiogenesis through the MEK/ERK/EIF4E/HIF1-α/VEGFA axis." (PMID 36941564, 2023). "Therefore, GAPDH, eIF4E and DNA polymerase α might be suitable targets for simultaneous inhibition to restrain growth of hepatocellular carcinoma cells by interrupting of energy supply, protein synthesis and DNA replication and ultimately triggering cell death." (PMID 25691059, 2015). "However, the role of JNK in mediating oxidative stress–induced eIF4E phosphorylation has been described in hepatocellular carcinoma, and JNK activation was noted to increase eIF4E phosphorylation in fetal MC lines." (PMID 39145446, 2024). "Although EIF4E, EIF4G3, NUDT4, and NUDT11 expression levels did not exhibit a statistically significant differential between neoplastic and normal samples, their expression displayed an upward trend in hepatocellular carcinoma (HCC) tissues." (PMID 40485623, 2025).